MAB21L2 (mab-21 like 2)
Description:
Required for several aspects of embryonic development including normal development of the eye.
Synonyms: MCOPS14; MCSKS14
Tractability: No criterion of Open Targets' tractability assessment is met for any kind of drug.
Gene: Protein-coding gene on chromosome 4 (150,582,151 to 150,584,693, forward strand). Ensembl gene ENSG00000181541.
Subcellular location: Nucleus; Cytoplasm
Subcellular location (Human Protein Atlas): Nucleoplasm
Gene Ontology:
Molecular function: protein binding
Biological process: eye development; nervous system development
Cellular component: cytoplasm; nucleoplasm; nucleus
Genetic constraint (gnomAD): Loss-of-function variants: 15 observed, 31.79 expected, observed/expected ratio (o/e) 0.47, 90% interval 0.31 to 0.73. The upper end of that interval is the gene's LOEUF score, 0.73, which puts it in group 2 of 6, group 1 being the genes least tolerant of losing a copy. Missense variants: 321 observed, 515.14 expected, observed/expected ratio (o/e) 0.62, 90% interval 0.57 to 0.68. Synonymous variants: 218 observed, 224.55 expected, observed/expected ratio (o/e) 0.97, 90% interval 0.87 to 1.09.
Gene-disease validity (ClinGen):
ClinGen rates the evidence that MAB21L2 causes each of these diseases.
colobomatous microphthalmia-rhizomelic dysplasia syndrome (autosomal dominant): Definitive.
Homologues: Orthologues: chimpanzee MAB21L2 (100% identical), macaque MAB21L2 (100% identical), dog MAB21L2 (99% identical), guinea pig MAB21L2 (99% identical), mouse Mab21l2 (99% identical), pig MAB21L2 (99% identical), rat Mab21l2 (99% identical), tropical clawed frog mab21l2 (97% identical), tropical clawed frog mab21l1 (93% identical), Drosophila melanogaster mab-21 (75% identical), Drosophila melanogaster CG4766 (74% identical), Caenorhabditis elegans mab-21 (56% identical). Paralogues in human: MAB21L1 (94% identical), MAB21L3 (25% identical), MAB21L4 (18% identical), CGAS (18% identical), ITPRIPL2 (16% identical), ITPRIP (16% identical), ITPRIPL1 (15% identical), MB21D2 (14% identical), TMEM102 (11% identical).
Diseases named in the same sentence as MAB21L2 in open-access papers:
MAB21L2 is named in the same sentence as 30 diseases in open-access papers, as found by Europe PMC text mining. Sharing a sentence is not in itself a finding about the gene and the disease. The quoted sentences say what the papers report.
microphthalmia (9 papers, 2014 to 2024). Congenital or developmental anomaly in which the eyeballs are abnormally small. "Here, we report a deletion upstream of an established gene for human AMC, MAB21L2, and demonstrate that the loss of tissue-specific enhancer elements within the deleted region leads to microphthalmia." (PMID 39455595, 2024). "New phenotypic associations were found for FOXE3 (bilateral sensorineural hearing loss) and MAB21L2 (unilateral microphthalmia)." (PMID 36192130, 2023). "Mab21l2 is involved in healthy eye development, and zebrafish carrying homozygous mab21l2 mutations display microphthalmia (smaller eyes)." (PMID 34472582, 2021). "Homozygous mab21l2u517 mutants showed microphthalmia (small eye) with a flattened retina, resembling eye defects observed in humans with mutations in its ortholog MAB21L2." (PMID 33416493, 2021). "Dominant variants in a close homolog of MAB21L1, MAB21L2, have been associated with microphthalmia and/or coloboma and repeatedly involved the same Arg51 residue, further supporting its pathogenicity." (PMID 33973683, 2021). "Here, we show that genes previously linked with microphthalmia, including aldh1a3, rx2, six6b, vsx2, and recently mab21l2 with anophthalmia, are constitutive elements of an Rx3-regulated gene network." (PMID 25266257, 2014). "While our study represents the first report of an upstream MAB21L2 deletion resulting in microphthalmia, 9 SNVs in the coding region of the gene have been identified in conjunction with AMC and variable additional features." (PMID 39455595, 2024). "In zebrafish, morpholino-mediated knockdown of mab21l2 resulted in microphthalmia and incomplete retinal development including discontinuous inner and outer plexiform layers." (PMID 25719200, 2015). "Disruption of the Otx2 transcription factor binding site in one of these elements (CE14) in Xenopus tropicalis reduced expression of mab21l2 in neurula stage embryos and resulted in microphthalmia, lens defects and coloboma, confirming its importance in eye development." (PMID 39455595, 2024). "A similar search of DR17 using the term microphthalmia resulted in 22 genes significant for the small eyes phenotype: Aldh1a3, Aff4, Bmp4, Cdk4, Cox6b1, Cxcr4, Dync1li1, Eef1d, Fgd1, Gne, Grh12, Mab21l2, Maf, Med13l, Mllt10, Mthfd2, Pex6, Phgdh, Ssr1, Stim1, Tdo2, and Vps26c." (PMID 36737727, 2023). "Similarly, zebrafish mab21l2 mutants, including knockdown and premature termination variants, display a variety of eye phenotypes, including microphthalmia, coloboma, small or absent lens, and misshapen optic cups." (PMID 39455595, 2024). "Given the presence of microphthalmia and coloboma in Individual III.5, we further investigated the impact of the deletion on MAB21L2 function." (PMID 39455595, 2024).
coloboma (4 papers, 2015 to 2024). An abnormality in which a part of a structure in one or both eyes is missing. "A whole exome sequencing project revealed four different MAB21L2 missense mutations in patients with ocular coloboma." (PMID 27271801, 2016). "In summary, we conclude that the MAB21L2 mutations associated with ocular coloboma lead to a protein with reduced stability because critical fold-stabilizing bonding networks are disrupted." (PMID 27271801, 2016). "Finally, our structure allows a molecular interpretation of the MAB21L2 mutations in ocular coloboma since the underlying residues and their interaction partners are conserved between L1 and L2." (PMID 27271801, 2016). "In this manuscript we present evidence for the role of MAB21L2 in human coloboma and further investigate its role in vertebrate ocular development by generation and analysis of zebrafish mab21l2 mutants." (PMID 25719200, 2015). "The severe coloboma observed in mab21l2R51_F52del embryos may point to the particular importance of domains located in the N-terminal region of mab21l2 for its proper functioning in the developing retina." (PMID 25719200, 2015).
osteoporosis (2 papers, 2012 to 2022). A condition of reduced bone mass, with decreased cortical thickness and a decrease in the number and size of the trabeculae of cancellous bone (but normal chemical composition), resulting in increased fracture incidence. "One of the genes that was enhanced expressed due to osteoporosis but also due to advanced age was MAB21L2 with FC[hMSC-old versus hMSC-C] = 2.7 and FC[hMSC-OP versus hMSC-C] = 14.4." (PMID 23028809, 2012). "Our data of age- and osteoporosis-induced expression of MAB21L2 in hMSC made us hypothesize that BMP-signaling in stem cells is less effective in advanced age and even less so in primary osteoporosis due to transcriptional repression of BMP-target genes." (PMID 23028809, 2012).
embryonic carcinoma (1 paper, 2004). "Our results, obtained in an anamniotic model system, the Xenopus embryo, and in murine embryonic carcinoma cells, indicate that MAB21L2 interacts functionally with SMAD1, a nuclear transducer of BMP2/4/7 signaling." (PMID 15613244, 2004).
microcephaly (1 paper, 2024). A congenital or acquired developmental disorder in which the circumference of the head is smaller than normal for the person's age and sex. "However, Individual III.5 also displayed phenotypes not previously observed in conjunction with MAB21L2 variants, including micrognathia and microcephaly." (PMID 39455595, 2024).
myelodysplastic syndrome (1 paper, 2022). A clonal hematopoietic disorder characterized by dysplasia and ineffective hematopoiesis in one or more of the hematopoietic cell lines. "Silencing of MAB21L2, as a TGFβ transcriptional repressor, was shown to induce an immune-suppressive microenvironment in myelodysplastic syndrome (MDS)." (PMID 35660939, 2022).
tumor (3 papers, 2022 to 2023). "The four GEO datasets and our clinical samples confirmed that the expression levels of CXCL10, IDO1, and MAB21L2 were significantly higher in tumor tissues than in control tissues (P < 0.05)." (PMID 37596528, 2023). "The expression of four TME-related genes (CXCL10, LZTS2, IDO1, and MAB21L2) that predict the TME signature of CRC was validated in four GEO datasets: GSE20916 (145 samples), GSE21815 (141 samples), GSE3629 (121 samples), and GSE89287 (71 samples), which contained normal control and tumor samples." (PMID 37596528, 2023).
cancer (2 papers, 2023). A tumor composed of atypical neoplastic, often pleomorphic cells that invade other tissues. "At the gene level, FDCSP (cancer cell migration and invasion), KIR2DL3 (immune response), SLC30A10 (antiapoptotic), MAB21L2, PCDH9 (cell adhesion), PEG3 (cell proliferation) were found to be highly expressed in the Lymph-node (LN)-positive samples." (PMID 37377901, 2023). "Compared with previous studies that investigated the value of TMEscore in other cancers, our study constructed a four-gene TME signature using TMEscore-related genes (CXCL10, LZTS2, IDO1, and MAB21L2), making it easy for clinicians to assess patients who might belong to the TME-H or TME-L signature." (PMID 37596528, 2023).
MAB21L2 also shares sentences with these, for which no sentence is quoted: Alzheimer disease (1 paper); aniridia (1); Anophthalmia (1); aphakia (1); breast carcinoma (1); cleft uvula (1); congenital cataract (1); craniosynostosis (1); developmental delay (1); gastric cancer (1); glaucoma (1); medulloblastoma (1); Micrognathia (1); microstomia (1); multiple sclerosis (1); optic disc coloboma (1); Peters anomaly (1); rectal cancer (1); Retinal coloboma (1); sensorineural hearing loss (1); Septo-optic dysplasia (1); thyroid tumor (1).